CD9 (CD9 molecule)
Diseases named in the same sentence as CD9 in open-access papers (continued):
Sharing a sentence is not in itself a finding about the gene and the disease.
malignant glioma (5 papers, 2015 to 2022). A grade III or grade IV glioma arising from the central nervous system. "In the current study, we specifically examined survivin and GFAP on the surface of serum-derived CD9+ exosomes from patients with recurrent malignant glioma who underwent investigational therapy consisting of active specific vaccination against survivin." (PMID 29383115, 2017). "In the malignant glioma patients receiving the anti-SVN vaccine, the CD9+/GFAP+/SVN+ and CD9+/SVN+ exosomes were released into the circulation while their early reduction after anti-SVN immunotherapy was related to longer progression-free survival." (PMID 34887381, 2021). "In patients with malignant glioma receiving anti-survivin immunotherapy, the decreased release of CD9+/GFAP+/SVN+ and CD9+/SVN+ exosomes may be related to the prolonged progression-free survival of patients." (PMID 33183286, 2020). "Finally, American researchers reported that the decreased release of circulating CD9+/GFAP+/SVN+ and CD9+/SVN+ exosomes in patients with malignant glioma, receiving anti-survivin immunotherapy, may be correlated with longer progression free survival." (PMID 36556468, 2022). "This study demonstrates that patients with malignant gliomas have CD9+/GFAP+/SVN+ and CD9+/SVN+ exosomes that are released into the circulation and that early reductions in their numbers following anti-survivin immunotherapy might be associated with longer progression-free survival." (PMID 29383115, 2017).
malignant mesothelioma (5 papers, 2013 to 2025). A malignant neoplasm of the pleura or peritoneum, arising from mesothelial cells. "Our present study focused on the molecular association between CD26 and CD9 and found that the interaction between these two molecules plays a significant role in invasiveness, motility, and proliferation of malignant mesothelioma cells." (PMID 24466195, 2014). "Since CD26 and CD9 have been reported to be associated with specific molecules, we attempted to determine the relationship between CD26 and CD9 in malignant mesothelioma cell lines." (PMID 24466195, 2014). "We found that CD26 and CD9 co-modulated and co-precipitated with each other in the malignant mesothelioma cell lines ACC-MESO1 and MSTO-211H." (PMID 24466195, 2014). "Our results also suggest that CD26 and CD9 serve as potential biomarkers as well as promising molecular targets for novel therapeutic approaches in malignant mesothelioma and other malignancies." (PMID 24466195, 2014). "Positive immunoreactivity for CD9 was observed in the membrane and cytoplasm of the tumor cells in 76 of 112 malignant mesothelioma cases." (PMID 23128478, 2013). "We recently reported that CD26 and CD9 are cancer stem cell markers of malignant mesothelioma." (PMID 24466195, 2014). "Therefore, combined application of anti-CD26 and anti-CD9 mAb is likely a promising therapeutic strategy for malignant mesothelioma." (PMID 24466195, 2014). "CD9 expression is an independent favorable prognostic marker of malignant mesothelioma." (PMID 23128478, 2013). "Therefore, combined blockade of both CD26 and CD9 might be a potential therapeutic approach for malignant mesothelioma." (PMID 24466195, 2014). "For example, in malignant mesothelioma, higher levels of CD9 expression are associated with a better prognosis, while reducing its expression leads to increased cell migration, suggesting that the lack of CD9 may contribute to greater invasiveness." (PMID 40860827, 2025). "More recently, we have identified CD9, CD24 and CD26 as cancer stem cell markers of malignant mesothelioma cells that correlated with primary stem cell signatures." (PMID 24466195, 2014).
oral cancer (5 papers, 2020 to 2023). "A more recent study showed that miR-24-3p was one of the most significantly upregulated miRNAs associated with CD9+ EVs from the saliva of patients with oral cancer." (PMID 33158181, 2020). "The exosomes obtained from the oral fluid of both oral cancer patients and healthy individuals showed a specific band at 28kDa area to represent CD9." (PMID 38059133, 2023). "Western blot can detect proteins CD63, Rab 5, CD9 and Alix in the exosomes derived from oral cancer patients." (PMID 38059133, 2023). "The concentration of CD9 in the exosomes of oral fluids of oral cancer patients was 104.1±18 pg/ml, while that in the exosomes in the oral fluids of healthy individuals was 152.9±24.4 pg /ml." (PMID 38059133, 2023). "More recently, label-free quantification was used to identify 415 proteins in CD63+/CD9+/TSG101+ EVs from the plasma of patients with oral cancer." (PMID 33158181, 2020). "Beyond this, a recent study demonstrated that CD63+/CD9+ EVs from the saliva of patients with oral cancers have unique and discriminatory infrared signatures compared with healthy controls." (PMID 33158181, 2020). "Despite CD63, CD81, and CD9 are downregulated in patients with oral cancer (OC)." (PMID 37304135, 2023). "Based on the traditional and well-established roles of these proteins, in particular HSP90, CD9+ EVs from oral cancer cells appear to be equipped to promote tumor growth and metastasis via actively contributing to protein folding, shuttling, and downstream signaling." (PMID 33158181, 2020). "Building on this, another study revealed that some miRNAs were exclusive (miR-302b-3p and miR-517b-3p) to CD63+/CD9+/Alix+/TSG101+ EVs from the saliva of patients with oral cancer compared with controls whereas others were up-regulated (miR-512-3p and miR-412-3p)." (PMID 33158181, 2020). "Oral fluids collected from oral cancer patients (n=36) and health individuals (n=25) was evaluated for amount of exosomal proteins CD63, CD9 and CD81." (PMID 38059133, 2023). "Therefore, a significantly reduced level of CD9 and CD81 expression, rather than an ambiguous increase in CD63 expression, can be used as an indicator of oral cancer, even in the early stages of the disease." (PMID 36707844, 2023).
osteoporosis (5 papers, 2013 to 2024). A condition of reduced bone mass, with decreased cortical thickness and a decrease in the number and size of the trabeculae of cancellous bone (but normal chemical composition), resulting in increased fracture incidence. "It was consistent with a role for vitamin K deficiency in the pathogenesis of osteoporosis associated with CD9–12." (PMID 29880866, 2018). "The clinical relevance is even more evident, as CD9 is abundantly expressed in OCs in osteoporosis and contributes to bone erosions of collagen-induced arthritis." (PMID 39220682, 2024). "Considering that CD9/CD81 DKO mice develop not only emphysema but also some of the extra-pulmonary diseases seen in COPD patients, such as body weight loss and osteoporosis, we regard these DKO mice as a novel model for human COPD32." (PMID 29572511, 2018). "Surprisingly, aged CD9/CD81 DKO mice developed not only emphysema but also non-pulmonary comorbidities such as osteoporosis and body weight loss, eventually leading to multiple aging phenotypes." (PMID 29572511, 2018). "Moreover, mice doubly deficient in CD9 and CD81 spontaneously develop pulmonary emphysema and osteoporosis, a phenotype akin to human COPD." (PMID 24040034, 2013). "We found that CD9/CD81 DKO mice with the COPD-like phenotype progressively develop an accelerated aging syndrome, with symptoms including cataracts, osteoporosis, emphysema, and atrophy of the skin, muscle, and adipose tissue." (PMID 29572511, 2018). "Third, CD9/CD81 DKO macrophages are spontaneously activated and produce more MMP-9 than WT macrophages, and CD9/CD81 DKO mice suffer from age-related pulmonary emphysema and osteoporosis, phenotypes akin to human COPD." (PMID 24040034, 2013).
pancreatic ductal adenocarcinoma (5 papers, 2023 to 2024). An infiltrating adenocarcinoma that arises from the epithelial cells of the pancreas. "For instance, in pancreatic ductal adenocarcinoma, CD9 mediated EV uptake from cancer-associated fibroblasts that promoted tumor development." (PMID 37007105, 2023). "The surfaces of the ANXA6+ cancer-associated fibroblasts isolated from patients with pancreatic ductal adenocarcinoma samples were abundant with CD9." (PMID 36826916, 2023). "Regarding stroma, high stromal CD9 evaluated with antibody clone C-4 was also associated with better survival of patients with pancreatic ductal adenocarcinoma, while positive tumor CD9 showed opposite results." (PMID 37007105, 2023). "ANXA6-EVs, derived from cancer-associated stromal fibroblasts (CAF), promotes tumor cell invasiveness in pancreatic ductal adenocarcinoma, and the blockade of CD9 impairs the uptake of ANXA6-EVs by pancreatic ductal adenocarcinoma cells." (PMID 37129645, 2023). "For example, CD9 enhances the placement of ASCT2 at the plasma membrane, thereby increasing glutamine absorption in pancreatic ductal adenocarcinoma." (PMID 39690134, 2024).
chronic obstructive pulmonary disease (4 papers, 2017 to 2024). A chronic and progressive lung disorder characterized by the loss of elasticity of the bronchial tree and the air sacs, destruction of the air sacs wall, thickening of the bronchial wall, and mucous accumulation in the bronchial tree. "CD9 and CD81 are two widely distributed and closely correlated TM4SFs, which can play preventive roles in systemic inflammation of chronic obstructive pulmonary disease (COPD)." (PMID 38725025, 2024). "For example, CD9 and CD81 share 45% identity, and double-deficient mice have macrophage dysfunction leading to a phenotype that resembles chronic obstructive pulmonary disease; neither single knockout has detectable disease." (PMID 28032533, 2017).
emphysema (4 papers, 2018 to 2024). "CD9/CD81 knockout mice are more susceptible to developing emphysema and atrophy of various organs, including muscle, thymus and testis, and even shorten survival." (PMID 38725025, 2024). "By analyzing transcriptomic data from transgenic mice deficient in Cd151 (an in vivo model of IPF) or Cd9 (an in vivo model of emphysema), we obtained deeper insights into their functions in lung pathology." (PMID 33424923, 2020). "Moreover, Cd9-deficient mice (Cd9KO) were prone to progressive emphysema, a major pathological component of COPD." (PMID 33424923, 2020). "Notably, CD9/CD81 DKO mice are more susceptible to cigarette-smoke-induced emphysema (manuscript in preparation)." (PMID 29572511, 2018). "Conversely, TGF-β signaling attenuation and TNF-signaling activation emerged as potentially novel functionaries of Cd9-deletion-induced emphysema." (PMID 33424923, 2020). "We further demonstrated that Cd9/Cd81 double-knockout mice spontaneously developed pulmonary emphysema and that Cd9 likely performs protective roles in lung inflammation and emphysema." (PMID 33424923, 2020). "No studies have linked TGF-β signaling with CD9, in the context of emphysema." (PMID 33424923, 2020). "Our analysis has provided novel insights into the contrasting roles of Cd151 and Cd9 in the pathogenesis of IPF and emphysema, respectively." (PMID 33424923, 2020). "Furthermore, Cd9-deletion “Activated” “MAPK signaling pathway” and “Chemokine signaling pathway,” both of which are consistent with increased lung inflammation and elevated pro-inflammatory cytokines in Cd9KO and are also consistent with phenotypes in emphysema." (PMID 33424923, 2020).
endometriosis (4 papers, 2021 to 2024). The growth of functional endometrial tissue in anatomic sites outside the uterine body. "Fallopian tube epithelial cells from endometriosis patients and controls were used as control samples, and CD9 and TSG101 were almost undetectable in the control samples." (PMID 37409222, 2023). "MenSCs from the endometriosis (E-MenSCs) women appear with the higher expression of CD9, CD10, and CD29 and the higher proliferation and invasion potentials than MenSCs from the non-endometriosis (NE-MenSCs) women." (PMID 34425902, 2021). "Expression of both CD9 and CD63, exosome surface marker proteins, was observed on exosomes from both the endometriosis and control groups." (PMID 34542679, 2022).
head and neck cancer (4 papers, 2019 to 2021). A primary or metastatic malignant neoplasm affecting the head and neck. "Also, low expression of CD9 was significantly connected with poor TTP in patients with head and neck cancer." (PMID 34868985, 2021).
Hypertension (4 papers, 2022 to 2025). The presence of chronic increased pressure in the systemic arterial system. "Elucidating these mechanisms requires additional research efforts to unravel the complexities of CD9 dynamics in the context of vascular aging and hypertension." (PMID 41356094, 2025). "Considering the emerging importance of CD9 in senescence, significant changes in exosomal CD9 expression in hypertensives indicate a novel insight to its potential links to vascular aging and hypertension that have yet to be uncovered." (PMID 41356094, 2025). "Three machine learning algorithms identified five biomarkers associated with hypertension: calmodulin 3 (CALM3), cluster of differentiation 9 (CD9), growth factor independence 1B transcriptional repressor (GFI1B), myosin light chain kinase (MYLK), and Ras suppressor-1 (RSU1)." (PMID 39519602, 2024). "The significantly reduced CD9 expression with unchanged TSG101 levels in hypertensive exosomes raises interesting questions about EV surface markers and their role in hypertension." (PMID 41356094, 2025). "The intersection of the three machine learning algorithms identified five genes as potential key biomarkers for hypertension: calmodulin 3 (CLAM3), CD9, growth factor independent 1B transcriptional repressor (GFI1B), myosin light chain kinase (MYLK), and Ras Suppressor Protein 1 (RSU1)." (PMID 39519602, 2024). "However, we found that CALM3 and CD9 did not exhibit significant expression differences between the hypertension and control groups, and ROC analysis indicated low reliability for these genes as hypertensive biomarkers." (PMID 39519602, 2024). "It is plausible that senescence-inducing stimuli might trigger the redistribution of CD9 to tissues rather than its participation in exosome biogenesis, potentially influencing the subtype of EVs released and the pathophysiology of vascular aging and hypertension." (PMID 41356094, 2025).
lung fibrosis (4 papers, 2016 to 2024). "We examined the changes in the levels of CD9-positive pan-EVs in the serum of mice that had been subjected to bleomycin-induced lung fibrosis." (PMID 27596748, 2016). "CD9+TREM2+ macrophages expressing GPNMB, SPP1, FABP5, and CD63 were reported in murine and human pulmonary fibrosis, enriched at the edges of scars." (PMID 37756565, 2023). "However, CD9+TREM2+CD63+ SAMs expressing Spp1 present in liver and lung fibrosis were presumed to have profibrotic role across species and tissues 24-26." (PMID 38505612, 2024).
metastatic carcinoma (4 papers, 2013 to 2025). A carcinoma which has spread from the original site of growth to another anatomic site. "K-M curves for LNM showed that a [high-ITGA3/CD9 and YK4] status can identify highly metastatic cancer capable of early lymph node invasion." (PMID 24006899, 2013).
metastatic melanoma (4 papers, 2013 to 2020). A melanoma that has spread from its primary site to another anatomic site. "NK cells that express CD9 were thought to only occur in the female reproductive system, however a CD9+ NK cell population was recently detected in the peripheral blood of metastatic melanoma patients." (PMID 24435119, 2014). "Moreover, western blot analysis of exosomal markers Alix, TSG101 and CD9 on plasma samples of four metastatic melanoma patients from the WT cohort confirmed that PA isolates EVs from these samples." (PMID 32978468, 2020). "Further analysis of the role of CD9+ leukocytes in progression of metastatic melanoma is warranted." (PMID 24435119, 2014).
Stroke (4 papers, 2022 to 2025). Sudden impairment of blood flow to a part of the brain due to occlusion or rupture of an artery to the brain. "Furthermore, the intracerebral administration of AEVs derived from ischemic astrocytes with anti-inflammatory properties, including CD63 and CD9 tetraspanins and miR-146a-5p, induced anti-inflammatory responses in the peri-infarct glial scars and facilitated stroke recovery." (PMID 37676390, 2024). "AEVs derived from reactive astrocytes with anti-inflammatory properties possess CD63 and CD9 tetraspanins and miR-146a-5p, which regulate glial scars by suppressing NF-κB and TNF-α, which permit axonal outgrowth, thereby improving stroke recovery." (PMID 37676390, 2024). "Based on previous work which identified CD9 (a key regulator of cell adhesion) as a receptor for some mouse PSGs, we postulated that rPSG1-Fc may decrease leukocyte infiltration into the ischaemic brain and thus promote stroke recovery via reduced adhesion molecule expression." (PMID 36120102, 2022). "In the current study we sought to assess levels of double-stained vesicles (CD171 + CD9 +, EAAT1 + CD9 +, and MOG + CD9 +), hereafter referred to as NDEs, ADEs, and oligodendrocyte-derived EVs (ODEs) respectively, over the first month post-stroke." (PMID 38438491, 2024).
brain tumor (3 papers, 2012 to 2023). "Using the public REMBRANDT database for brain tumors, we confirmed the prognostic value of CD9, whereby a more than two fold up-regulation correlates with shorter patient survival." (PMID 26573230, 2016).
breast tumors (3 papers, 2010 to 2021). "Low CD9 expression in primary breast tumors is associated with higher metastatic potential, and CD9 gene expression is commonly downregulated in lymph node metastases compared to primary breast tumors." (PMID 32224917, 2020). "CD9 is strongly expressed and co-localizes with integrin alpha-3 throughout normal mammary luminal epithelial cells and in the PyMT breast tumor cells at different stages of tumorigenesis." (PMID 32224917, 2020). "It will be particularly important to test the role of HuR upon CD9 and CALM2 expression in breast tumors in vivo." (PMID 20370918, 2010).
esophageal squamous cell carcinoma (3 papers, 2013 to 2025). Esophageal squamous cell carcinoma (ESCC) is a type of esophageal carcinoma (EC) that can affect any part of the esophagus, but is usually located in the upper or middle third. "Therefore, the role of CD9 in esophageal squamous cell carcinoma is inconsistent and lacks systematic research, especially the role of CD9 in ESCC radiation resistance." (PMID 40860827, 2025). "Similar associations between reduced CD9, greater invasiveness, and metastatic potential are reported in laryngeal squamous cell carcinoma (LSCC) and esophageal squamous cell carcinoma (ESCC)." (PMID 41322905, 2025). "Further stratified analysis by histological subtypes demonstrated that CD9 mRNA levels were markedly higher in esophageal squamous cell carcinoma (ESCC) than in esophageal adenocarcinoma (EAC) (P<0.0001), suggesting a potential subtype-specific role of CD9 in ESCC pathogenesis." (PMID 40860827, 2025).
invasive breast carcinoma (3 papers, 2018 to 2025). A carcinoma that infiltrates the breast parenchyma. "In patients with invasive breast cancer, it was shown that CD9 on immune cells was associated with a longer disease free survival, while CD9 expression on the tumor cells showed the opposite effect." (PMID 29896201, 2018). "In addition, the level of CD9 in tumor and matrix immune cells of patients with invasive breast cancer has different roles." (PMID 40860827, 2025). "Moreover, CD9 expression may have prognostic significance for lobular carcinoma and invasive breast carcinoma, depending on the histology of the CD9-expressing cells (tumor or stromal immune cells) and the molecular subtype." (PMID 40565320, 2025).